AMOT (angiomotin)
Diseases named in the same sentence as AMOT in open-access papers (continued):
Sharing a sentence is not in itself a finding about the gene and the disease.
systemic sclerosis (1 paper, 2014). A chronic disorder, possibly autoimmune, marked by excessive production of collagen which results in hardening and thickening of body tissues. "In a mouse model for systemic sclerosis, an autoimmune connective tissue disorder characterized by oxidative stress, impaired vascular function, and attenuated angiogenesis, NIR stimulated angiogenesis by increasing angiomotin and decreasing angiostatin expression in the ischemic hind limb." (PMID 25202275, 2014).
tumor (35 papers, 2006 to 2025). "It is thought that tumor suppressor angiomotin/merlin at TJ in epithelial cells, is directly linked to the pathogenesis of cancer via the hippo pathway." (PMID 27036040, 2016). "The shorter splice variant of angiomotin, p80 that is a membrane-associated protein is expressed in tumor and placental endothelium and mediates endothelial cell migration in vitro." (PMID 21385454, 2011). "In fact, the levels of both analogues decrease in tumours that are associated with metastasis and mortality, which is in clear contrast with that of angiomotin." (PMID 16430777, 2006). "Kaplan-Meier survival analysis has shown that patients bearing tumours with high levels of angiomotin were associated with a shorter overall survival (119.9 (105.2–134.7 95% CI) months vs 136.5 (124.5–148.4, 95%CI) months for patients with low angiomotin transcript, p < 0.05)." (PMID 16430777, 2006). "In a follow-up study in 2012, the angiomotin DNA vaccine demonstrated efficacy in reducing tumor growth and increasing tumor-free survival in transgenic and transplantable tumor models." (PMID 39081320, 2024). "Amotl2, which encodes a Motin family member, Angiomotin-like 2, is a tumor suppressor that negatively regulates the YAP and TAZ function via AMOT-mediated tight junction localization." (PMID 37414763, 2023). "Accordingly, Almog and colleagues, reported that angiomotin and tropomyosin were upregulated in dormant tumour cells, while EphA5 was increased in the blood of mice with dormant tumour cells." (PMID 35563661, 2022). "Accordingly, recent studies revealed AMOT proteins as tumor suppressors in glioblastoma, ovarian cancer and lung cancer." (PMID 33467643, 2021). "The prognostic DEmiRNA, hsa-miR-337-3p targeting one DEmRNA (AMOT, a witnessed oncogene in OSCC), has been implicated to target AMOT, HOXB7, MMP-14, PTEN and acted as a tumor suppressor through sponging oncogene." (PMID 31141819, 2019). "In vivo xenograft experiments also demonstrated that the TPA efficacy with respect to tumor growth inhibition was much reduced when YAP or AMOT was knocked down." (PMID 28322318, 2017). "All of these results argue that the growth inhibitory effects of XAV939 in Hippo pathway mutant tumor cells were primarily due to its inhibition of TNKS-mediated angiomotin degradation." (PMID 27144834, 2016). "AMOTL2, the most abundant angiomotin in both resistant H2052 and sensitive H2373 tumor cells, showed lower and less durable stabilization in H2052 cells in response to XAV939." (PMID 27144834, 2016). "Intriguingly when co-expressed together, ITCH and AMOT/p130 were shown to suppress cell growth, confirming an anti-tumor effect of ITCH." (PMID 25350971, 2014). "Since tumor growth is dependent on vascularization, metastatic dormancy is generally associated with the upregulation of anti-angiogenic proteins such as angiomotin, which suppresses tumor growth while maintaining the dormant state of DTCs." (PMID 24062983, 2013). "This study suggests that antiangiogenic proteins such as angiomotin, which has been shown to suppress tumor growth and keep dormancy of tumor metastases, are upregulated during dormancy." (PMID 22448123, 2012). "Since xenogeneic proteins frequently break tolerance against self-antigens, a plasmid expressing the human p80 isoform of angiomotin was administered to different tumor-bearing mouse models." (PMID 21385454, 2011). "Using multivariate analysis of the following factors, nodal status, tumour grade, angiomotin, angiomotin-like-1 and angiomotin-like-2, we have found that nodal status (p = 0.0185) and angiomotin transcript (p = 0.031) were independent survival factors." (PMID 16430777, 2006). "Levels of angiomotin were at significantly higher levels in grade 2 and grade 3 tumours compared with grade 1 (p < 0.01 and p = 0.05 respectively)." (PMID 16430777, 2006). "The presence of angiomotin and the angiomotin-like transcripts were detected in both normal and tumour mammary tissues." (PMID 16430777, 2006).
tumor (continued). "First, angiomotin is highly expressed in aggressive tumours (grade 2 and 3 and tumours with nodal involvement) than in less aggressive tumours." (PMID 16430777, 2006). "Additionally, FIHKO in cancer cells, particularly lung cancer, was shown to suppress tumor growth in an orthotopic lung tumor model by increasing angiomotin (Amot), a key component of the Hippo tumor suppressor pathway." (PMID 40343532, 2025). "However, combining the angiomotin DNA vaccine with another targeting extracellular and transmembrane domains of human Her-2 resulted in dramatic tumor growth impairment in the transgenic model, demonstrating increased tumor-free survival." (PMID 39081320, 2024). "Thus, the role of AMOT proteins in tumor formation and their interplay with WWC proteins are obviously variable depending on the affected cell type or organ." (PMID 33467643, 2021). "The AMOT gene family members function as tumor suppressors in several human cancers." (PMID 33658392, 2021). "In liver, Amot-p130 acts as a tumorigenesis facilitator when associated to Yap cofactor, while, in prostate AMOTp80, not AMOT p130, functions as a tumor promoter by enhancing PCa cell proliferation." (PMID 28441737, 2017). "Indeed, targeting angiomotin by DNA vaccination efficiently inhibited angiogenesis and tumor growth in vivo." (PMID 21385454, 2011). "However, mice treated with a combination of angiomotin and Her-2 vaccine were 80% tumor-free compared to 20% of mice treated with the Her 2 vaccine alone when followed up to 70 weeks after birth." (PMID 21385454, 2011). "The important biological role of angiomotin and its analogues indicates that it may play an important role in angiogenesis in tumours." (PMID 16430777, 2006). "However, the expression, distribution pattern and the clinical implications of angiomotin in other tumour types are yet to be explored." (PMID 16430777, 2006). "However, studies have yet to verify whether AMOT acts as an oncoprotein or a tumor suppressor, because its effect on tumor growth differs depending on the cancer cell type." (PMID 35740678, 2022). "KRAS–STAT4 pathway targets a Y chromosome gene KDM5D, which inhibits the expression of tight junction proteins angiomotin (AMOT) and MHC-I through epigenetic regulation, ultimately driving tumor metastasis and immune escape in a male-specific manner." (PMID 39872442, 2024). "On the other hand, AMOT and AMOTL2 have also been observed to have a tumor suppressor role in ovarian cancer and glioblastoma, respectively, where their downregulation in cells avails YAP for its nuclear function and enhances cell proliferation." (PMID 36768425, 2023). "AMOT acts as an oncoprotein by increasing the activity of YAP in hepatic carcinoma, but it acts as a tumor suppressor by repressing the activation of YAP target genes in ovarian cancer." (PMID 35740678, 2022). "In addition, angiomotin and tropomyosin (the binding proteins of angiostatin and endostatin, respectively) may mediate anti-angiogenic activities in dormant tumour cells, while Eph receptor 5 (EphA5), a receptor tyrosine kinase involved in angiogenesis, may be linked to dormancy." (PMID 35563661, 2022). "Scaffold proteins angiomotin negatively regulated the transcription factors YAP and TAZ by preventing their nuclear translocation, suggesting a tumor-suppressing role of AMOT family proteins as components of the Hippo pathway." (PMID 32983988, 2020). "For example, AMOT, AMOTL1, as well as AMOTL2 exert both oncogene or tumor suppressive gene in different cancer types." (PMID 29650031, 2018). "Of the class II OAs found to be overexpressed in tumor ECs during BALB-neuT cancer progression, the most promising is angiomotin (Amot), a member of the Motin protein family." (PMID 25136593, 2014). "The role of angiomotin (AMOT) in cancer is currently quite controversial and might depend on the cancer type, because its function both as an oncogene and tumor suppressor was reported." (PMID 41469472, 2025).
tumor (continued). "A similar role for AMOT was described in PSC neural commitment, while inhibitors of Tankyrase have been recently proposed to negatively regulate YAP by stabilizing AMOT in tumor cells." (PMID 33116297, 2021). "We found that AMOTp80, but not AMOT p130, functioned as a tumor promoter by enhancing PCa cell proliferation." (PMID 28052036, 2017). "All of these findings establish that TNKS inhibitors antagonize Hippo pathway mutant tumor cells primarily through angiomotin stabilization independent of other TNKS functions." (PMID 27144834, 2016).
cancer (26 papers, 2006 to 2026). A tumor composed of atypical neoplastic, often pleomorphic cells that invade other tissues. "The loss of AMOT/Merlin enhances the cell migration, invasion and proliferation of cancer cells via the Hippo/YAP pathway." (PMID 28071680, 2017). "Elevated ΔNp63 expression, regulated via non-canonical interactions with polarity and junctional proteins (e.g., AMOT, ZO-1/2), associates with cancer stem-like properties, EMT and drug resistance, and the ΔNp63/YAP ratio enables molecular subtyping and risk stratification." (PMID 40486910, 2025). "This action competes with RNF146-mediated degradation, leading to stabilization of tankyrase and its binding partner, Angiomotin, a cancer cell signaling protein." (PMID 37938264, 2023). "Genes with known implications in cancer, such as MMP-13, KRT84, OLFM4, GJA1, AMOT and ADAMTS1, were strongly linked to DSG3 overexpression." (PMID 38067138, 2023). "Angiomotin (AMOT) was originally identified as an angiostatin binding protein and is associated with the pathogenesis of cancer." (PMID 34944960, 2021). "Loss of AMOT/Merlin induces TEAD/AREG via the Hippo/YAP pathway and promotes the cell migration, invasion and proliferation of cancer cells." (PMID 34944960, 2021). "AMOT promotes either YAP1 nuclear localization or cytoplasmic retention in different cancer types." (PMID 29650031, 2018). "In some specific cancer types, oncogenic functions of AMOT have also been revealed." (PMID 29650031, 2018). "Authors of all three studies did not report adverse effects thus suggesting that targeting of endothelial cell markers such as angiomotin, TIE-2 and DLL-4, in anti-angiogenic design offers a safe and promising avenue for cancer vaccine therapy." (PMID 39081320, 2024). "Although AMOT is an upstream co‐activator of YAP1, YAP1 binds to the enhancer of AMOT and induces its expression in human cancer cells, suggesting a possible feedback control." (PMID 36775869, 2023). "The immunophilin FKBP51, the angiomotin AmotL2, and the scaffoldin IQGAP1 are overexpressed in many types of cancer, with the highest increase in leucocytes from patients undergoing oxaliplatin chemotherapy." (PMID 35563891, 2022). "Bioinformatic analysis revealed that 14 of the 44 (32%) potential KDM4A-KIKAT/LINC01061 target genes were found in the cancer-related pathways identified in KIKAT/LINC01061-overexpressing SLK cells, and AMOT was one of them." (PMID 34111227, 2021). "Taken together, the functional roles of AMOT-p80, AMOT-p130, AMOTL1, and AMOTL2 in different cancer types are controversial and they highly depend on cell context." (PMID 29650031, 2018). "Removal of the tumor suppressor angiomotin (AMOT)/Merlin from the TJ position induces TEAD/AREG via the Hippo/YAP pathway and then enhances the migration, invasion and proliferation of cancer cells." (PMID 28071680, 2017). "However, in some cancers, including renal, hepatic and ovarian cancer, there is also evidence for a YAP-activating role of AMOT in the nucleus, and a recent study identified the involvement of an AMOT-binding long noncoding RNA in this nuclear activity." (PMID 32326412, 2020). "Furthermore, removal of the tumor suppressor AMOT/Merlin from the TJ position induces TEAD/AREG via the Hippo/YAP pathway and then enhances the migration, invasion and proliferation of cancer cells." (PMID 28071680, 2017). "Therefore, phospholipid-binding of Angiomotin is a key regulatory mechanism of TJ/polarity disassembly during epithelial dedifferentiation (e.g., EMT), qualifying Angiomotin as an oncogene in some cancer types." (PMID 32411703, 2020).
AMOT also shares sentences with these, for which no sentence is quoted: meningioma (2 papers); prostate carcinoma (2); cholangiosarcoma (1); chronic kidney disease (1); glioblastoma (1); head and neck squamous cell carcinoma (1); hepatocellular carcinoma (1); hypersomnia (1); liver disease (1); lymph node metastasis (1); melanoma (1); mesothelioma (1); neurological diseases (1); thyroid carcinoma (1); X-linked intellectual disability (1).